NRP2 (neuropilin 2)
Diseases named in the same sentence as NRP2 in open-access papers (continued):
Sharing a sentence is not in itself a finding about the gene and the disease.
lymphoma (3 papers, 2013 to 2019). A malignant (clonal) proliferation of B- lymphocytes or T- lymphocytes which involves the lymph nodes, bone marrow and/or extranodal sites. "The expression levels and functional activities of SEMA3B, SEMA3F, and Neuropilin-2 have furthermore been investigated in leukemias and lymphoma cells." (PMID 31143707, 2019). "Moreover, SEMA3F and its receptor Neuropilin-2/NRP2 were found to be highly expressed in human T-cell acute lymphoblastic leukemia/lymphoma primary cells, but SEMA3F was shown to inhibit the migration of malignant cells induced by CXCL12 and S1P." (PMID 31143707, 2019). "Moreover, NRP2 and SEMA3F are expressed in human T-cell acute lymphoblastic leukemia/lymphoma primary cells." (PMID 25068647, 2014). "Based on our results regarding normal T cell precursors, we hypothesized that NRP2 and SEMA3F could also be expressed by malignant T cell precursors and have a role on lymphoblast migration which may explain various clinical patterns of disease presentation e.g. leukemic vs. lymphoma." (PMID 25068647, 2014).
occlusive vascular diseases (3 papers, 2020 to 2024). "NRP2 is upregulated by vascular cell types in response to injury/inflammation and is involved in numerous processes associated with the development of occlusive vascular diseases." (PMID 32708258, 2020). "With these observations in mind, it is tempting to speculate that NRP2 marks a more dedifferentiated VSMC—a hallmark of many occlusive vascular diseases." (PMID 32708258, 2020). "Additionally, because NRP2 promotes PDGFbb and TGFβ-induced VSMC migration, proliferation, and loss of SMC contractility, it may be beneficial to inhibit NRP2 as a therapeutic strategy to treat occlusive vascular diseases." (PMID 32708258, 2020). "Other studies have implicated Nrp2 in endothelial-to-mesenchymal transition during occlusive vascular disease, following activation of Nrp2/TGFβ/TGFβR1 complexes." (PMID 38592275, 2024). "NRP2 supports lymphangiogenesis and neovascularization, and its inhibition might be a promising therapeutic approach for occlusive vascular diseases." (PMID 39417451, 2024). "Separately, inhibiting Nrp2 may also have benefits for the treatment of occlusive vascular diseases (via VEGF-C/Nrp2 signaling, PDGFβ, and TGFβ signaling)." (PMID 38592275, 2024). "Here, we review recent studies implicating NRP2 in the development of occlusive vascular diseases and discuss how NRP2 could be targeted for therapeutic intervention." (PMID 32708258, 2020). "Here, we discuss recent studies implicating NRP2 in the development of occlusive vascular diseases and consider how NRP2 could be targeted for therapeutic intervention." (PMID 32708258, 2020). "However, whether it is beneficial to target EC-derived NRP2 to treat occlusive vascular diseases is most likely context dependent." (PMID 32708258, 2020). "Therefore, inhibiting VEGF-C/NRP2 driven signalling could potentially be used therapeutically in the treatment of occlusive vascular diseases." (PMID 32708258, 2020).
pancreatic adenocarcinoma (3 papers, 2011 to 2021). "Of note, the endothelial integrin α5 could also trans-interacted with neuropilin 2 (NRP2) on cancer cells, promoting the vascular extravasation in pancreatic adenocarcinoma mouse xenograft models." (PMID 34869579, 2021). "Moreover, in another study, NRP2 expression was found in 5 out of 6 (83%) commonly used pancreatic cell lines and in 7 out of 11 (64%) surgical specimens of pancreatic adenocarcinoma by IHC staining." (PMID 21747928, 2011).
papillary thyroid cancer (3 papers, 2017 to 2023). "For example, in papillary thyroid cancer, NRP2 could promote cell growth and is closely associated with extrathyroid extension and lymph node metastasis." (PMID 34516335, 2021). "Previous studies have shown that PLXNB1 can induce epithelial-mesenchymal transformation (EMT) and promote metastasis of head and neck squamous cell carcinoma, and NRP2 can promote tumor progression of thyroid papillary carcinoma." (PMID 36460803, 2023).
preeclampsia (3 papers, 2017 to 2024). Preeclampsia is a hypertensive disorder of pregnancy that is characterized by new-onset hypertension with proteinuria presenting after 20 weeks of gestation, and depending on mild or severe forms may initially present with severe headache, visual disturbances, and hyperreflexia. "In this regard, high SEMA3C levels have been found at the maternal–fetal–placental interface during the first trimester of gestation, and SEMA3F, SEMA3B, and NRP2 are overexpressed in the placenta of women with preeclampsia." (PMID 38541683, 2024). "A recent report documented reductions of the axon guidance ligand semaphorin 3F (Sema 3F) and its receptor, neuropilin 2 (NRP2), expression in pregnant women with preeclampsia, another putative risk factor for ASD." (PMID 30635860, 2019). "We hypothesized that placenta ischemia, featuring preeclampsia, might induce the down-regulation of the anti-angiogenic system represented by semaphorin 3F and its receptor, NRP-2, in the attempt to improve placenta angiogenesis and blood supply." (PMID 28350837, 2017).
renal carcinoma (3 papers, 2011 to 2021). A carcinoma arising from the epithelium of the renal parenchyma or the renal pelvis. "Moreover, they inhibited the proliferation of VEGFC-expressing renal cancer cells through NRP2 signaling." (PMID 34067671, 2021).
thyroid cancer (3 papers, 2014 to 2019). "To investigate the role of NRP2 in thyroid cancer, we have chosen the FB-2 cell line and selected stable cell clones overexpressing PAX8." (PMID 26030152, 2015). "In contrast, the motility of the two overexpressing PAX8 clones is significantly decreased; suggesting that NRP2 downregulation strongly reduces the migration ability of FB-2 thyroid cancer cells." (PMID 26030152, 2015). "All together, our results indicate that NRP2 is involved in cell migration and invasion capabilities of FB-2 thyroid cancer cells." (PMID 26030152, 2015). "Here, we demonstrate that in mouse thyroid carcinomas resembling papillary, follicular, and anaplastic carcinomas, the expression of NRP2 is strongly increased." (PMID 26030152, 2015). "To examine whether high levels of NRP2 could directly contribute to the tumorigenicity of thyroid cancer cells, we analyzed whether NRP2 downregulation, mediated by PAX8 re-expression, was able to modify the oncogenic properties of FB-2 cells." (PMID 26030152, 2015). "NRP-2 also promotes the invasion and migration of thyroid cancer cells in vitro, an effect that could be blocked by a neutralizing anti-NRP-2 antibody." (PMID 24142150, 2014). "Notably, ectopic overexpression of PAX8 in FB-2 thyroid cancer cells promotes Neuropilin-2 downregulation producing a significant reduction in cell proliferation, migration ability, and invasion activity and reverting the cell phenotype from mesenchymal to a more epithelial one." (PMID 26030152, 2015). "We also show that the downregulation of NRP2 mediated by PAX8 reduces cell proliferation and suppresses cell migration and invasion of thyroid cancer cells." (PMID 26030152, 2015). "Moreover, it is interesting to note that the expression of NRP2, an important paralog of the NRP1 gene, has been correlated to lymph node metastasis of human PTC and is required in the VEGF-C/NRP2 mediated invasion and migration of thyroid cancer cells." (PMID 31614935, 2019). "Interestingly, we observed an inverse correlation between the expression of PAX8 and Neuropilin-2 in thyroid carcinoma tissues and cell lines compared to non-tumor counterparts, suggesting a critical role of PAX8 in regulating Neuropilin-2 expression in vivo." (PMID 26030152, 2015).
Arthritis (2 papers, 2022). Inflammation of a joint. "Functional enrichment further supported that the primed genes are heavily involved in inflammatory response, arthritis-promoting functions (Ccl2, Cxcl5, Sphk1) and, interestingly, Wnt pathway (Bmp2, Rspo3, Cd44) and stem cell differentiation (Sox5, Nrp2, Cdk6)." (PMID 35879783, 2022).
autism spectrum disorder (2 papers, 2019 to 2021). A spectrum of developmental disorders that includes autism, and Asperger syndrome. "Consistent with its developmental roles, the neuropilin 2 (Nrp2) locus contains polymorphisms in patients with autism spectrum disorder (ASD)." (PMID 34663783, 2021). "Genome-wide association and other genetic studies have implicated at least 500+ genes associated with the occurrence of autism spectrum disorders (ASD) including the human semaphorin 3F (Sema 3F) and neuropilin 2 (NRP2) genes." (PMID 30635860, 2019).
clear cell Renal Cell Carcinoma (2 papers, 2017 to 2025). "Single-cell RNA sequencing (scRNA-seq) analyses were performed on tumours from clear cell Renal Cell Carcinoma (ccRCC) and skin cutaneous melanoma (SKCM) which exhibit the highest expressions of NRP1 and NRP2, respectively." (PMID 40134439, 2025).
liver cancer (2 papers, 2018 to 2023). An epithelial or non-epithelial malignant neoplasm that arises from the liver. "The expression changes of VEGFC/D-VEGFR3/NRP2 and SDF1/CXCR4 are almost completely identical between tumor cells and normal cells, between high and low lymph node metastatic potential of liver cancer cells as well as between downregulation and upregulation of AnnexinA7 (unpublished data)." (PMID 29783989, 2018).
liver fibrosis (2 papers, 2022 to 2023). "Deletion of either SEMA3C or its receptor NRP2 in activated HSCs reduced liver fibrosis in mice." (PMID 36551769, 2022).
medulloblastoma (2 papers, 2022 to 2023). A malignant, invasive embryonal neoplasm arising from the cerebellum. "Another study reported that low expression of miR-466f-3p promoted more mesenchymal phenotype in medulloblastoma stem cells through Vegfa-Nrp2 signaling pathway." (PMID 35392967, 2022). "In SHH medulloblastoma, the downregulation of miR-466f-3p, together with the concordant upregulation of VEGFa and Neuropilin 2, encouraged cell proliferation and the self-renewal ability of CSCs through the EMT process, which sustained the mesenchymal phenotype of SHH medulloblastoma CSCs." (PMID 37370764, 2023).
meningioma (2 papers, 2013 to 2021). A generally slow growing tumor attached to the dura mater. "To our knowledge, we are the first group reporting on NRP-1 and NRP-2 protein levels in WHO grade II and III meningiomas." (PMID 33528717, 2021). "In our study, we investigated VEGF-A, the receptors VEGFR-1-3 and their major co-receptors NRP-1 and NRP-2 in a cohort of 147 WHO grade II and III meningioma patients in order to elaborate potential therapeutic targets." (PMID 33528717, 2021).
metastasis (2 papers, 2021). The spread or migration of cancer cells from one part of the body (where they first appeared) to another. "Osteoclasts express NRP2 and are reported to be early propagators of PCa bone metastasis." (PMID 33990538, 2021).
metastatic cancer (2 papers, 2016 to 2019). A carcinoma which has spread from the original site of growth to another anatomic site. "It was revealed that either downregulation of NRP2 or upregulation of WDFY1 can be an effective way to promote cell death in metastatic cancer." (PMID 30871059, 2019). "Thus, inhibiting NRP2 or hyper-activating WDFY1 can be an effective strategy to induce cell death in metastatic cancer." (PMID 27026195, 2016). "All these information would be important for targeting the NRP2 axis in treating metastatic cancer." (PMID 27026195, 2016). "Furthermore, downregulation of NRP2 or upregulation of WDFY1 can promote cell death in metastatic cancer by controlling the signaling of VEGFRFs and maybe a potential target-based anticancer therapy." (PMID 30871059, 2019).
myelofibrosis (2 papers, 2024 to 2025). A partial or complete replacement of the bone marrow stroma by fibrous tissue. "Advanced myelofibrosis was characterized by stromal spindle-shaped cells expressing both NRP2 and NCAM1 in aggregates and diffusely within the bone marrow space resulting in progressive osteosclerosis with anastomosing spicules." (PMID 38792002, 2024). "First, we assessed NRP2 immunohistochemical expression patterns in BM trephine biopsies of myelofibrosis patients in situ." (PMID 38792002, 2024). "This study investigates the role of neuropilin 2 (NRP2) in myelofibrosis and bone formation, identifies the type of stromal cells expressing and upregulating NRP2 and outcomes when NRP2 is lost." (PMID 38792002, 2024). "In fact, NCAM1 and NRP2 protein expression correlated with the severity of myelofibrosis in our clinical cohort." (PMID 38792002, 2024). "In order to gain more information regarding Nrp2 involvement in myelofibrosis, we examined the expression of the genes introduced above in established murine models of MPN-associated fibrosis." (PMID 38792002, 2024). "Here, we evaluated NRP2 as a mesenchymal stromal cell target in myelofibrosis by using mouse and human bone marrow and scRNAseq data." (PMID 38792002, 2024). "Given its function in TGFβ signaling, NRP2 emerges as an interesting novel druggable target to ameliorate myelofibrosis and osteosclerosis simultaneously in PMF patients." (PMID 38792002, 2024). "Our data suggest that modulation of NRP2 in patients with myelofibrosis may be beneficial to counteract fibrosis and osteosclerosis and first studies show that NRP2 modulation results in low toxicity profiles." (PMID 38792002, 2024). "In summary, NRP2 represents a potential novel druggable target in patients with myelofibrosis." (PMID 38792002, 2024). "Together, these findings suggest that Nrp2 and Ncam1 double-expressing cells represent rare MSC able to differentiate toward the fibrotic and the osteogenic trajectory driving myelofibrosis and osteosclerosis." (PMID 38792002, 2024). "Murine ThPO and JAK2V617F myelofibrosis models showed co-expression of Nrp2 and Ncam1 in osteolineage cells, while fibrosis-promoting MSC only express Nrp2." (PMID 38792002, 2024). "Consistent with and extending our in situ findings in clinical patients, Nrp2 was also expressed in profibrotic, osteogenic and inflammatory MSC and osteolineage cells in murine myelofibrosis models by scRNAseq analysis, supporting its possible role as a druggable target in MPN." (PMID 38792002, 2024). "During early myelofibrosis in PMF, NRP2 and NCAM1 expression was increased in the endosteal niche." (PMID 38792002, 2024). "Lack of NRP2 expression in Schwann cells in this dataset is particularly interesting, as neuropathy has been reported to worsen myelofibrosis in MPN." (PMID 38792002, 2024).
osteoarthritis (2 papers, 2017 to 2022). A noninflammatory degenerative joint disease occurring chiefly in older persons, characterized by degeneration of the articular cartilage, hypertrophy of bone at the margins and changes in the synovial membrane. "Immunohistochemical studies have localized neuropilin-2 to sympathetic nerve fibers in synovial tissue from patients with RA and osteoarthritis, so expression of semaphorin receptors by sympathetic neurons and nerve fibers continues in adults." (PMID 29270174, 2017). "It was determined that semaphorin 3G is expressed in RA but not in the osteoarthritis synovium; its receptor neuropilin-2 is primarily expressed on activated macrophages." (PMID 35659346, 2022).
pulmonary fibrosis (2 papers, 2024 to 2025). Chronic progressive interstitial lung disorder characterized by the replacement of the lung tissue by connective tissue, leading to progressive dyspnea, respiratory failure, or right heart failure. "Neuropilins, particularly NRP2, represent promising druggable targets in the treatment of pulmonary fibrosis." (PMID 41159753, 2025). "NRP2 is a clinically druggable target in pulmonary fibrosis." (PMID 38792002, 2024). "This could explain that in contrast to NRP1 inhibition, no significant hematologic impairment has been observed in phase III clinical trials targeting NRP2 in pulmonary fibrosis (NCT03824392, NCT04412668)." (PMID 38792002, 2024).
renal cell carcinoma (2 papers, 2020 to 2025). "Studies have previously reported NRP1 to complex with ITGA5 in HUVECs and NRP2 to complex with ITGA5 from co-cultures between HUVECs and renal cell carcinoma." (PMID 32528960, 2020). "For example, both NRP2 and PLXNA1 are significantly upregulated in renal cell carcinoma (the Human Protein Atlas), which may be a promising target cancer type for therapeutic investigations of P1943-Nb2cL." (PMID 41391772, 2025).
sarcoidosis (2 papers, 2023 to 2025). Sarcoidosis is a multisystemic disorder of unknown cause characterized by the formation of immune granulomas in involved organs. "The role of NRP2 in sarcoidosis is largely unknown, however NRP2 expression was found in sarcoid granulomas." (PMID 37334374, 2023).
squamous cell carcinoma (2 papers, 2017 to 2022). A carcinoma arising from squamous epithelial cells. "We analyzed the transcriptional expression of SEMA3F and NRP2 in a cohort of 53 patients with cN0 squamous cell carcinoma treated with an elective neck dissection." (PMID 35565388, 2022).
tongue cancer (2 papers, 2020 to 2024). A malignant neoplasm affecting the tongue. "NRP2 plays an important role in regulating lymphangiogenesis, and findings from a clinical trial for patients with early-stage tongue cancer showed that cytoplasmic NRP2 was associated with metastasis and a poor prognosis." (PMID 38172098, 2024).
acromesomelic dysplasia (1 paper, 2018). A group of extremely rare, inherited, progressive skeletal conditions that result in a particular form of short stature, called short-limb dwarfism. "In contrast, in humans attenuated NP signalling from loss-of-function NRP2 mutations cause autosomal recessive acromesomelic dysplasia with extreme short stature (MIM# 602875); heterozygous carriers display reduced height (MIM# 616255)." (PMID 29883787, 2018).
acute lymphoblastic leukemia (1 paper, 2017). Leukemia with an acute onset, characterized by the presence of lymphoblasts in the bone marrow and the peripheral blood. "In a study aimed at identifying molecular markers for susceptibility and resistance to Vγ9Vδ2 T cells in acute lymphoblastic leukemias and non-Hodgkin’s lymphomas, NRP2 was enriched in the resistant tumor samples." (PMID 29067024, 2017). "NRP2 and Sema3F were also detected in T-cell acute lymphoblastic leukemia (T-ALL) and T-cell lymphoblastic lymphoma (T-LBL) samples and modulated migration in response to CXCL12 and S1P in a similar fashion in the former." (PMID 29067024, 2017).
AIDS (1 paper, 2022). A syndrome resulting from the acquired deficiency of cellular immunity caused by the human immunodeficiency virus (HIV). "The results suggest that different CMV-infected cells in the different sites of the GI relating to the expression level of PDGFRα and Nrp2 as well as the vital part of pathological assessment in diagnosing and managing CMV among HIV/AIDS cases." (PMID 35027044, 2022).
allergic asthma (1 paper, 2019). A asthma with a basis in a pathological type I hypersensitivity reaction. "NRP2 variant rs849558:T > C was marginally associated with atopy and allergic asthma." (PMID 30206357, 2019).
Allergy (1 paper, 2019). An allergy is an immune response or reaction to substances that are usually not harmful. "Using variant-based analyses, FYCO1, CXCR6 and NRP2 shed new light to mechanisms influencing allergy." (PMID 30206357, 2019).
Alzheimer disease (1 paper, 2020). A progressive, neurodegenerative disease characterized by loss of function and death of nerve cells in several areas of the brain leading to loss of cognitive function such as memory and language. "The genes represented by the age‐DMRs included a few notable members such as Cyp46a1 and Abca7, which are involved in cholesterol metabolism and implicated in Alzheimer's disease, and few members of the WNT signaling and mesenchyme developmental pathways (e.g., Fzd1, Fzd8, Wnt5a, Jak3, Ptk7, Nrp2)." (PMID 32790008, 2020).